VIM (vimentin)
Diseases named in the same sentence as VIM in open-access papers (continued):
Sharing a sentence is not in itself a finding about the gene and the disease.
breast carcinoma (continued). "In addition, we suggested evidence that sensitivity of paclitaxel resistant breast cancer cells to this combination treatment correlates with EMT process by blocking HIF-1α, vimentin, Snali, and Slug and by activating E-cadherin in paclitaxel resistant breast cancer cells." (PMID 34942984, 2021). "In oesophageal and breast cancer cells, IL-6 exposure has been shown to promote mesenchymal/fibroblastic morphology, migration and invasion in vitro and in vivo, associated with reduced CD24, KRT19, EpCAM and E-cadherin expression and increased vimentin, N-cadherin and MMP9 levels." (PMID 34361105, 2021). "Thus, CDH2 and VIM are both bona fide markers of breast cancer EMT." (PMID 34831167, 2021). "Importantly, TRPM7 mediated calcium signals further modulate EMT in breast cancer cells, which TRPM7 deficiency specifically reduces EGF-induced STAT3 phosphorylation and the expression of Vimentin, suggesting that TRPM7 is required for maintaining a mesenchymal feature in breast cancer cells." (PMID 32211326, 2020). "Considering tumor volume growth and the decrease of TGF-β, Vimentin, and Twist expression in this study, it looks like the correlated chain, mediating between these regulation factors, can be known as a noble mechanism for the effect of interval aerobic training on breast cancer." (PMID 32405368, 2020). "However, EMT is not sufficient by itself to facilitate spontaneous breast cancer metastasis: the non-metastatic variant of the 4T1 cell line, 67NR was shown to express high levels of vimentin and N-Cadherin, and yet it is not invasive or metastatic." (PMID 32796899, 2020). "In human mammary epithelial cells or breast cancer cells, EMT-associated transcription factors, including Snail1 and Twist1, could up-regulate this cytoskeletal structure, and vimentin filaments, a known marker for EMT, supported extension of these microtentacles." (PMID 32391382, 2020). "Therefore, we further explored whether CD133+ HPCs could affect the EMT process in breast cancer cells to promote invasion by quantifying the relative levels of E-cadherin, N-cadherin and Vimentin expression using Western blot assays." (PMID 33243165, 2020). "To determine whether chemerin treatment influences EMT in breast cancer cells, we investigated the expression level of E-cadherin as an epithelial marker and those of vimentin and β-catenin as mesenchymal markers in MDA-MB-231 and MCF-7 cells exposed to chemerin." (PMID 32325994, 2020). "Since PC4 silencing could increase the migration and invasiveness in breast cancer cell lines, the expression pattern of different MMPs, mesenchymal markers like fibronectin, vimentin and regulators of EMT like, Zeb1 and Zeb2 was investigated upon silencing of PC4 in these cells." (PMID 31839879, 2019). "In addition, VIM is one of the most filamentous proteins, expressed in various types of cancers, such as prostate, gastrointestinal, central nervous system, pulmonary, and breast cancers." (PMID 31294654, 2019). "To investigate the actinomycin V effects on Epithelial-mesenchymal transition inhibition in human breast cancer cells, we preformed the Western blot analysis to evaluate the expression levels of the epithelial marker E-cadherin, and mesenchymal markers N-cadherin and Vimentin in MDA-MB-231 cells." (PMID 31137656, 2019). "Furthermore, BEP inhibited EMT of breast cancer cells, which was determined by an increased gene expression of the epithelial gene, keratin 19, and decreased gene expression of the mesenchymal gene, vimentin when compared to control." (PMID 30691094, 2019). "Furthermore, recent evidence has indicated that miR-137 could diminish the expression of Vimentin and N-cadherin and elevate that of E-cadherin in breast cancer cells, indicating that the overexpression of miR-137 may lead to the suppression of EMT." (PMID 31143092, 2019).
breast carcinoma (continued). "In addition, miR-30a inhibits vimentin expression, which may serve as a tumor biomarker for predicting breast cancer outcome and assist in the development of a potential therapeutic target for this disease." (PMID 30181714, 2018). "The results showed that BP could inhibit migration and invasion in breast cancer cells via the up-regulation of the epithelial marker E-cadherin and down-regulation of mesenchymal markers N-cadherin and vimentin, and the down-regulation of transcription factor Twist in both breast cancer cell lines." (PMID 29370116, 2018). "Increased vimentin expression in non-invasive cells was marked by the cells displaying an increased motility and invasiveness suggesting that increased expression in breast cancer may mediate metastasis and invasion." (PMID 28616237, 2017). "It has been shown that CD44s expression levels are associated with the mesenchymal phenotype in breast cancer and hepatocellular carcinoma, and has been implicated in promoting EMT, evidenced by decreased E-cadherin expression and increased N-cadherin and Vimentin expression." (PMID 29137308, 2017). "Similarly, the C1q expression in mesenchymal and immune cells was corroborated by double-staining immunofluorescence analyses of invasive colon and breast cancer specimens using markers specific for epithelial (pan-cytokeratin), mesenchymal (vimentin) or immune cells (CD45)." (PMID 26831747, 2016). "The expression of vimentin in this study correlates with its possible role in cancer invasiveness and therefore proposes the different hypothesis in which vimentin in breast cancer could derive from breast progenitor cells with bilinear differentiation potential." (PMID 27110560, 2016). "Moreover, co-expression of TNC and vimentin might induce mesenchymal-like phenotype in breast cancer cell." (PMID 27391030, 2016). "A study of breast cancer tissue specimens revealed a positive correlation between the expression levels of miR-7 and E-cadherin, and a negative correlation between the expression levels of miR-7 and Vimentin, indicating miR-7 might be involved in the metastasis of breast cancer." (PMID 26516313, 2015). "Finally, expression of E-cadherin was down-regulated, while expression of N-cadherin and vimentin was up-regulated, in primary breast carcinomas with metastasis and their metastatic foci, compared with primary breast carcinomas without metastasis and benign breast lesions." (PMID 26702618, 2015). "Early studies suggested the involvement of EMT in aggressive breast cancer behaviour as cells exhibiting a mesenchymal-like phenotype (vimentin expression, lack of cell border associated uvomorulin) show dramatically increased motility, invasiveness, and metastatic potential in nude mice." (PMID 25140302, 2014). "Furthermore, knockdown of CHD5 in T-47D cells reduced the expression of the epithelial marker E-cadherin and increased the expression of mesenchymal marker vimentin, suggesting that CHD5 loss could induce EMT in CHD5-positive breast cancer cells." (PMID 22569290, 2012). "Moreover, vimentin is selectively expressed in aggressive breast cancer cell lines." (PMID 19695088, 2009). "Similar findings have been seen in breast cancer, with DHA decreasing metalloproteases such as MMP2 and MMP9 as well as vimentin and reducing cell migration." (PMID 41009329, 2025). "In breast cancer cells, hypoxia increases uPAR expression, which facilitates SNAIL nuclear translocation, E-cadherin downregulation, vimentin upregulation, and ultimately EMT and migration." (PMID 40361472, 2025). "For instance, miR-17-5p directly targets vimentin in colorectal cancer, miR-20a inhibits EMT by suppressing TWIST1 and TGFBR2 in breast cancer, and miR-22 blocks Snail expression and the MAPK1/Slug/vimentin feedback loop in bladder cancer." (PMID 40806587, 2025).
breast carcinoma (continued). "Upregulated of E-cadherin and Occludin, but decreased levels of N-cadherin, Vimentin, and Snail expression were detected in the breast cancer cell lines upon VEGF or NRP1 silencing in the breast cancer cells." (PMID 40277760, 2025). "Established markers for breast cancer cells (BRCA1, MAP3K1, BMPR1A) and fibroblasts (FN1, VIM, COL6A2) were used to classify the clusters." (PMID 39805002, 2025). "The results showed that F. nucleatum infection significantly inhibited the expression of the epithelial marker E-cadherin, while promoting Vimentin expression, thus facilitating EMT in breast cancer cells." (PMID 40589632, 2025). "Our data demonstrated that SAMD4B overexpression downregulated E-cadherin while upregulating N-cadherin, Vimentin, Snail, and Slug, suggesting that SAMD4B promotes EMT in breast cancer cells." (PMID 41154652, 2025). "In the metastasis process, our previous report shows that endocrine-resistant breast cancer (MCF-7/LCC9) overexpressed EMT genes, including vimentin and snail, and had lower E-cadherin expression compared to wild-type (MCF-7) cells." (PMID 40569965, 2025). "CAFs-derived TGF-β drives EMT and enhances fibronectin, vimentin, MMP-2/9, SNAIL, and TWIST expression, promoting breast cancer cell motility, drug resistance, and stemness via upregulation of lncRNA HOTAIR, silencing tumor suppressor genes." (PMID 40230452, 2025). "In the vast majority of studies, baicalin inhibits breast cancer metastasis by targeting migration, invasion, and EMT, upregulating E-cadherin, and downregulating mesenchymal markers like Vimentin and N-cadherin." (PMID 40136435, 2025). "The importance of the molecular characterization of breast cancers is underscored by the paradoxical prognostic impact of BMP-2 and vimentin across different cancer subtypes." (PMID 39859358, 2025). "Breast cancer cells exposed to fibronectin promote EMT by increasing the expression of both N-cadherin and vimentin, thereby enhancing cell migration and invasion." (PMID 40361472, 2025). "In breast cancer, fibronectin binding to integrins activates FAK, triggering EMT and upregulating N-cadherin and vimentin, leading to enhanced cell migration and invasion." (PMID 40173050, 2025). "Another overexpressed in breast cancer lncRNA is ROR that induces EMT by inhibiting miR-205 activity, hence preventing degradation of genes such as N-cadherin, vimentin, and ZEB1." (PMID 39912983, 2025). "Slug-mediated vimentin expression was reported to regulate EMT and maintain migratory activity in breast cancer." (PMID 39990676, 2025). "The expression of PAR1 on breast cancer cells causes a loss of epithelial markers such as E-cadherin and gain of mesenchymal markers including vimentin, shifting them to an invasive phenotype and allowing a HMG2A mediated invasion of breast cancer." (PMID 39982274, 2025). "Vimentin (VIM) is an epithelial-mesenchymal transition marker expressed in some types of cancer, including breast cancer." (PMID 38963646, 2025). "Utilizing the 4T1 breast cancer cell model, we first used RNA‐seq and proteomics to investigate the changes in the APA of PICK1 following VIM knockout (KO)." (PMID 39781570, 2025). "A previous study in breast cancer showed that known EMT markers such as N-cadherin and vimentin are expressed similarly in both partial- and full-EMT states, while SNAIL expression is higher in partial-EMT states, with decreasing expression in full-EMT." (PMID 40936697, 2025). "In this scenario, several molecules involved in both EMT and bone mineralization, such as vimentin, bone morphogenetic proteins (BMPs), RANKL, and SDF-1 have been proposed as possible prognostic biomarkers of breast cancer." (PMID 39859358, 2025). "Specifically, in this study, we perform immunohistochemical and bioinformatic analyses to investigate the possible prognostic role of vimentin, SDF-1, BMP-2, BMP-4, PTX3, OPN, RANKL, and Runx2 on a large cohort of breast cancer patients." (PMID 39859358, 2025).
breast carcinoma (continued). "Research has shown that APOC1 increases vimentin expression and decreases E-cadherin levels, promoting EMT in breast cancer cells." (PMID 39873475, 2025). "According to the hierarchical clustering analysis of 52 breast cancer cell lines, SOD2 and GPX8 genes were part of the mesenchymal gene signature and co-clustered with ZEB1, VIM, and SNAI2." (PMID 38172210, 2024). "Our discovery, coupled with the finding of a correlation of VIM expression with increased NESs of EMT pathways, confirms Vim as a marker for the spontaneous EMT phenotype in breast cancer." (PMID 39256881, 2024). "While Vimentin and Slug protein levels decreased after 200 μg/mL OLE-mALG treatment to 3D breast cancer culture, E-cadherin levels increased." (PMID 38722566, 2024). "The expression levels of VIM, KRT5 and KRT17 in normal samples were significantly higher than those in breast cancer samples." (PMID 38581422, 2024). "Conversely, MCF7 luminal A breast cancer cells leading collective invasion co-expressed E-cadherin, N-cadherin, ZEB1, Snail, Twist, and vimentin." (PMID 39408880, 2024). "In our study, we found that the expression levels of FXR, vimentin and SLC7A11 were significantly higher in breast cancer tissues, particularly in metastatic cancer tissues compared to non-metastatic ones." (PMID 39543094, 2024). "In breast cancer, CAF markers such as FAP, α-SMA, Vimentin, FSP1, PDGFRα, PDGFRβ, Caveolin-1, and PDPN have been validated." (PMID 39519118, 2024). "The reduction in the EMT marker vimentin aligns with previous findings that SAA1 knockdown affects vimentin expression, suggesting a possible link between SAA and EMT regulation in breast cancer." (PMID 39336082, 2024). "We then examined the effects of Trametinib on the highly ordered subcellular organization of vimentin in various cell types, including A549 lung epithelial cells, L929 mouse fibroblasts, THP-1 macrophages, and MDA-231 breast cancer cells." (PMID 38429984, 2024). "In our study, we found that Brazilin promoted E-cadherin expression, decreased actin polymerization, vimentin expression, MMPs secretion and cell invasion of MCF7 and MDA-MB-231 breast cancer cells." (PMID 38737746, 2024). "Treatment with Etinostat, an HDAC inhibitor, reduced vimentin and N-cadherin expression and rescued E-cadherin expression in MDA-MB-231 breast cancer cells." (PMID 39409910, 2024). "In breast cancer cells, miR-708-3p inhibits EMT by directly targeting ZEB1, cadherin 2, and vimentin." (PMID 38920689, 2024). "Breast cancer cells treated with calcitriol decrease the expression of ZEB1, N-cadherin, vimentin, or integrins and increase the level of E-cadherin, suggesting that calcitriol reduces the EMT process." (PMID 38360633, 2024). "In MDA-MB-468 breast cancer cells, YODA 1 activation resulted in an increase in vimentin and a decrease in E-cadherin." (PMID 38632473, 2024). "We found that EO compounds effectively decrease the expression/activation of VIM, SLUG, and SNAIL, inhibiting migration and invasion of breast cancer cells." (PMID 40259961, 2024). "After knocking down MYO1D, the protein levels of N-cad and vimentin were reduced in MDA-MB-231 and BT-549 cells, which inhibited EMT (epithelial cell-to-mesenchymal transition) in breast cancer cells in comparison to the control group." (PMID 38512527, 2024). "For example, in breast cancer, the presence of EMT markers such as vimentin and N-cadherin, as well as drivers of EMT, such as Snail and Twist, is associated with an aggressive phenotype and poor clinical outcomes." (PMID 38324529, 2024). "Increased expression of vimentin and MMP9 can be found in various epithelial cancers, including lung, colorectal, and breast cancer." (PMID 38388902, 2024). "In contrast, the expression of vimentin and N-cadherin increased in HCC1806-TaxR cells, indicating the progression of EMT in this breast cancer cell line that has developed resistance to taxol." (PMID 38674115, 2024).
breast carcinoma (continued). "YODA 1-mediated Ca2+ influx induced a concentration-dependent decrease in the epithelial marker, E-cadherin, and a concentration-dependent increase in the mesenchymal marker, vimentin, in MDA-MB-468 breast cancer cells." (PMID 38632473, 2024). "In breast cancer cells, RING finger protein 208 (RNF208) is found to play an inhibitory role in metastasis by interacting with phosphorylated Vimentin Ser39 residues." (PMID 38191501, 2024). "In a tumor derived from human breast cancer stem cells grown in a mouse mammary fat pad, the expression of RUNX1 inhibits and the expression of RUNX2 and vimentin enhances the tumor growth." (PMID 38630262, 2024). "Breast cancer patients with lymph node metastasis, distant metastasis or late TNM stage luminal-like subtype (stage III&IV), have higher levels of SLC7A11 and vimentin." (PMID 39543094, 2024). "In a study on breast cancer, ALA-treated MDA-MB-231 and 4T1 breast cancer cell lines both exhibited downregulated expression of EMT markers such as Snail, vimentin, and Zeb1, along with impaired cell migration capabilities." (PMID 39199143, 2024). "This cascade results in reduced invasiveness and migration of breast cancer cells by inhibiting EMT markers, such as Snail, Slug, and vimentin." (PMID 38339408, 2024). "Claudin-low breast cancer is characterized by low expression of Claudin3, 4, 7, E-cadherin, and HER2 and high expression of Vimentin, Snai 1/2, Twist 1/2, Zeb 1/2, and ALDH1, as well as stem cell characteristics." (PMID 37904877, 2023). "In a study on breast cancer, SNAI1 was found to be an EMT-inducing factor as it downregulated E-cadherin, upregulated vimentin, and induced classical morphologic changes of EMT." (PMID 36766756, 2023). "In contrast, the HS578T-Hyg breast cancer cells are in a M state due to the expression of “classical” M markers, such as CDH2, VIM, ZEB1 and WNT5A." (PMID 38139138, 2023). "Expressions of CD90, CD73, vimentin and N-cadherin also reported in MDA-MB-231 cell or other breast cancer cells." (PMID 36768815, 2023). "Among different subgroups in breast cancer scRNAseq data, significant correlations between EMP1/COL3A1 and three EMT genes (CDH1, VIM, and CTNNB1) were found in c16 fibroblasts." (PMID 38187400, 2023). "In the TCGA dataset, we assessed the expression of key epithelial marker E-cadherin (CDH1) and mesenchymal markers, including vimentin (VIM), MMP9, SNAI2, ZEB1, and ZEB2, about VISTA expression in breast cancer patients using Spearman correlation analysis." (PMID 37152039, 2023). "The application of high-dose VC also led to the increased expression of the epithelial marker E-cadherin and the reduced expression of the mesenchymal marker vimentin, indicating the role of VC in inhibiting EMT in breast cancer cells." (PMID 38067361, 2023). "As a cancer suppressor miRNA, it completely inhibits breast cancer metastasis and chemotherapy resistance by regulating MT (directly targeting EMT activators, such as ZEB1, CDH2, and vimentin)." (PMID 37809692, 2023). "A fluorescent image was taken of the MDA MB 231 breast cancer cells and Vimentin-RFP tagged knock in EMT MDA-MB-231 cells detecting the constitutively expressed Vimentin gene by red fluorescence." (PMID 37538932, 2023). "Formalin-fixed paraffin-embedded (FFPE) humanbreast cancer tissue sections were stained for multiplex MALDI-IHCwith six photocleavable mass-tagged (PC-MT) antibodies constitutinga breast cancer antibody panel (CD20, actin-αSM, HER2, CD68,vimentin, and panCK)." (PMID 36638208, 2023). "By comparison of the expression of EMT‐markers between different stages of breast cancer, overexpression of ZEB2 (p = .04) and vimentin (p = .04) and down expression of E‐cadherin (p = .03) was observed in advance stages." (PMID 37088469, 2023).